MTOR (mechanistic target of rapamycin kinase)
Diseases named in the same sentence as MTOR in open-access papers (continued):
Sharing a sentence is not in itself a finding about the gene and the disease.
cancer (continued). "Mammalian target of rapamycin (mTOR) is a highly conserved eukaryotic protein kinase that coordinates cell growth and metabolism, and plays a critical role in cancer, immunity, and aging." (PMID 36095197, 2022). "The PI3K-Akt-mTOR signaling pathway is one of the most frequently deregulated biochemical cascades in various types of cancer." (PMID 36142768, 2022). "Samotolisib is a novel dual inhibitor targeting phosphoinositide 3-kinase (PI3K) and the mammalian target of rapamycin (mTOR), and has undergone several phase-II clinical trials as a potential treatment for different cancers." (PMID 35563377, 2022). "In the high-risk group, the genes were linked to autophagy and cancer pathways, including MAPK, MTOR, PPAR, regulation of autophagy, and WNT signalling." (PMID 35459137, 2022). "The PI3K/Akt/mTOR pathway is typically activated in cancer tissue and can maintain tumor growth; inhibition of the PI3K/Akt signaling pathway has been proposed as a therapeutic target." (PMID 36553542, 2022). "Autophagy inducer rapamycin is used as an mTOR inhibitor for cancer therapy to decrease proliferation and increase autophagy." (PMID 36611970, 2022). "Nonetheless, dual mTORC1 and mTORC2 inhibitors targeting the PI3K/AKT/mTOR pathway in the treatment of malignant tumors are still being investigated." (PMID 35402264, 2022). "It has been shown that mTOR activation has an antitumor effect in hypoxic TAMs but a tumor-promoting effect in cancer cells." (PMID 35874739, 2022). "The rationale is to interrupt DNA replication with SG and exploit potential synergy with an agent targeting the PI3K/AKT/mTOR pathway needed for cancer cell survival, proliferation and invasion." (PMID 35877237, 2022). "BEZ235 is a dual PI3K and mTOR inhibitor that has shown considerable efficacy against a wide range of different cancer cell lines including ovarian, breast and bladder cancers." (PMID 35053555, 2022). "These inhibitors show high potency and little drug resistance even at low doses, suggesting that PI3K/mTOR inhibitors are promising cancer drugs." (PMID 35614940, 2022). "The PI3K/AKT/mTOR pathway is activated in most human cancers, increasing the secretion of VEGF through HIF-1-dependent or HIF-1-independent mechanisms and modulating angiogenesis by regulating the expression of NO and angiopoietins." (PMID 34852710, 2022). "As previously discussed, the role of molecular damage in cancer supports the role of mTOR-driven hyperfunction in aging." (PMID 35533376, 2022). "This study investigated the clinical benefit of the tissue-agnostic application of mTOR inhibitors for the therapeutic management of a pan-cancer cohort of patients with mTOR pathway aberrations." (PMID 35454843, 2022). "The AKT/mTOR signaling pathway, generally known to be activated in cancer, is also responsible for cancer progression." (PMID 35327484, 2022). "Many mTOR inhibitors have been approved by the FDA for the treatment of cancer, but a large number of them are still being investigated in numerous clinical trials." (PMID 35682571, 2022). "Several OVs combined with mTOR inhibitors such as Everolimus and rapamycin showed synergistic effect against several cancer cells." (PMID 36513720, 2022). "Compound 14 can mechanically regulate the cellular PI3K/Akt/mTOR pathway by inhibiting the phosphorylation of Akt and S6 in human cancer cell lines." (PMID 35614940, 2022). "PI3K/Akt/mTOR signaling pathway involved in cell survival, growth, and proliferation is the commonly activated signaling pathway in human cancers." (PMID 35402264, 2022). "Because everolimus has the higher affinity for mTOR/FKBP12 and has already been approved for cancer treatment, we selected it as the candidate mTOR/ABC transporter inhibitor." (PMID 34551970, 2022).
cancer (continued). "In this study, we performed in silico screening of mTOR-binding compounds and identified lomitapide, an FDA-approved drug, as a candidate to inhibit mTOR and its signaling in cancer cell growth." (PMID 35831271, 2022). "Rapamycin is useful in the treatment of various cancers due to its inhibitory effect on the PI3K/AKT/mTOR pathway." (PMID 35847007, 2022). "NDV infection of cancer cells activates PI3K/Akt/mTOR, p38 MAPK/Mnk1, and CDK-Rb-E2F oncogenic pathways which help viral mRNA translation." (PMID 35327364, 2022). "Aberrant AKT/mTOR pathway activation is broadly seen in various malignant tumors with a consequence of accelerating cellular proliferation, increasing cancerous resistance to apoptosis and advancing the invasion and metastasis of tumors." (PMID 35615533, 2022). "LAT1 expression correlates with proliferation of cancer cells enabling rapid growth as it plays role in cell growth, transcription and translation through the mammalian target of rapamycin (mTOR) signalling pathway which facilitates protein synthesis." (PMID 36434486, 2022). "Nutrient sensing plays a major role in the activation of mTOR1, and mTOR drives cancer metabolic reprogramming." (PMID 36227107, 2022). "PI3K/mTOR dual inhibitors are considered to be critical in cancer treatment and have been used in clinical trials." (PMID 35614940, 2022). "Under the stress of chemotherapy, mTOR inhibition promotes cancer cells to adopt a reversible drug-tolerant senescence state, which supports survival and allows for effective DNA repair, but incidentally, leading to chemoresistance and tumor recurrence." (PMID 36396656, 2022). "Here the authors also discuss the involvement of mTOR in the polarization of TAMs into the immunosuppressive M2 phenotype, which favors cancer progression and survival." (PMID 35327484, 2022). "Downregulation of mTOR has widely been found in multiple human cancers, such as breast, prostate, lung, liver, and renal carcinomas." (PMID 35587712, 2022). "Given the importance of the mTOR pathway in various diseases, especially in most cancers, inhibitors targeting key players in the pathway have undergone therapeutic development." (PMID 35740927, 2022). "Resolvin E1 inhibits oxidative stress, autophagy, and apoptosis by targeting Akt/mTOR signals, suppresses tumor growth, and enhances cancer therapy." (PMID 35155234, 2022). "USP21 promotes KRAS∗-independent cancer development via the mTOR signaling pathway by MARK3-mediated up-regulation of macropinocytosis, which helps to fulfil the anabolic requirements." (PMID 36046825, 2022). "Hyperactivation of the mTOR pathway is a common occurrence in malignancies as it promotes carcinogenesis and cancer growth." (PMID 35454843, 2022). "By cBioPortal and Weighted Gene Co-expression Network Analysis of The Cancer Genome Atlas and Genotype-Tissue Expression databases, mTOR signaling pathway was correlated with PD-L1 dysregulation in gastrointestinal cancers." (PMID 35201501, 2022). "Inhibitors of the mTOR signaling pathway have been developed to treat some types of malignant tumors." (PMID 35082928, 2022). "mTOR is the target gene of miR-100-5p that decreases its expression, enhancing drug sensitivity in cancer cells." (PMID 36091133, 2022). "The PI3K/AKT/mTOR pathway is widely dysregulated almost in all human cancers and is pivotal to cancer cell proliferation, survival, and therapy resistance." (PMID 35832194, 2022). "In breast and other cancers, metformin activates the AMPK signaling pathway and inhibits the mTOR pathway to trigger its anti-cancer effects." (PMID 35222283, 2022). "In cancer studies, miR-520a has been associated with suppression of oncogenic signaling pathways including CDK4, SUV39H1, LIMK1, GOT-2, AKT1/mTOR, and PI3K/AKT31–37." (PMID 35149732, 2022).
cancer (continued). "ATP-competitive (catalytic) inhibitors of mTOR that can deactivate both mTORC1 and mTORC2 are currently used for some solid tumors as anti-cancer agents, and as immune-modulator after various organs transplantation to prevent virus associated nephropathy." (PMID 36476132, 2022). "PI3K/mTOR presents an important oncogenic pathway in HCC whose inhibition has shown anti-cancer potential." (PMID 35897659, 2022). "mTOR is also responsible for mediating T cell differentiation through metabolic adaptations, and for promoting immune response to cancer processes." (PMID 35955882, 2022). "It has been reported that the up-regulation of mTOR in malignant tumors facilitates aerobic glycolysis, promotes cell proliferation, and prevents autophagy." (PMID 35242138, 2022). "PTEN is a well-known tumor suppressor and is commonly inactivated in multiple cancers, playing key role in regulating the PI3K/AKT/mTOR pathway which effects cancer cell survival." (PMID 35132337, 2022). "The mTOR pathway performs an indispensable role in nutrient metabolism, energetic regulation, and promotion of cancer cell survival." (PMID 35515121, 2022). "LAT1 inhibition by JPH203 treatment has been reported to suppress mTOR in cancer cells, and targeting LAT1 have been suggested to be synergized with rapamycin for cancer therapy." (PMID 36357940, 2022). "TWIST2 can suppress the expression of FGF21 to activate the AMPK/mTOR signalling pathway which inhibits the progression of various cancers." (PMID 36118870, 2022). "When combined with cisplatin, metformin increased the AKT/mTOR pathway-mediated inhibition of cancer." (PMID 36397350, 2022). "Expression of HIF1α is commonly regulated by hypoxia, but, particularly in cancer, can also be modulated by other factors, such as inhibitors of mammalian target of rapamycin (mTOR)." (PMID 36093095, 2022). "The finding that mTOR is hyperactive in human cancers and plays a key role in Akt-mediated cancer development in mouse models suggests that mTOR is a potential target for human cancers." (PMID 36180910, 2022). "mTOR signaling pathway plays an important role in the cancer immunity and many other biological funcions." (PMID 35201501, 2022). "Temsirolimus is a selective mTOR inhibitor, it binds to the intracellular protein FKBP-12, and the complex FKBP-12/temsirolimus binds to mTOR, which controls the division of cancer cells, thus inhibiting its activity." (PMID 36109789, 2022). "Although previous work has highlighted the role of mTOR in the process of cancerization, the specific involvement of mTOR signaling in the different types of cancer, as well as the pathways of mTOR inhibition, remain poorly discussed." (PMID 36428613, 2022). "Although this result was not consistent with the mechanism that 4E-BP1 was a direct target of mTOR, in some cases, it was also reported that 4E-BP1 was phosphorylated in an mTOR-independent manner in some cancer cells." (PMID 35847100, 2022). "The study concluded that the crosstalk between PI3K/Akt/mTOR pathways was essential to mediate the various mechanisms involved in the multiple pathways to induce the inhibitory effect on the cancer cell lines under study." (PMID 36365094, 2022). "Hyperactivated mTOR signaling marks some types of cancer and promotes proliferation and tumor progression." (PMID 36555369, 2022). "Activation of AMPK leads to reduced mTOR signalling; this is relevant in highly-mitotic tissues such as cancer where metformin treatment can slow cell proliferation." (PMID 34505282, 2022). "The PI3K/AKT/mTOR signaling pathway has been reported to regulate a series of cellular behaviors including cell proliferation, migration, and apoptosis in cancer cells." (PMID 36061190, 2022).
cancer (continued). "A KEGG pathway enrichment analysis led to the identification of four classical signaling pathways regulating oncogenesis and metastasis: focal adhesion, gap junction, mTOR signaling, and proteoglycans in cancer." (PMID 35433481, 2022). "The PI3K/Akt/mTOR signaling pathway is aberrantly activated in many human malignant tumors, and blocking the PI3K/Akt/mTOR pathway has emerged as a new therapeutic target for multiple cancer cells." (PMID 36104717, 2022). "The functional impacts of miR-99b-5p on regulating mTOR expression and cellular locations, cell apoptosis, and cytotoxic chemotherapy in these cancer cell lines were assessed by using immunofluorescence, Western blot, TUNEL, and apoptosis assays." (PMID 36077039, 2022). "AKT is a kind of effector in the PI3K/AKT/mTOR pathway of tumors and is a potential target in treating cancer." (PMID 36539659, 2022). "Activation of the protein kinase B (Akt)/mechanistic or mammalian target of rapamycin (mTOR) plays a vital role in regulating cell survival and suppressing autophagy in cancer cells." (PMID 36612260, 2022). "Although a number of PI3K/AKT/mTOR axis inhibitors have been studied in pre-clinical settings, only a few reached the approval for the treatment of human cancer." (PMID 35565291, 2022). "PI3K, Akt, and mTOR expression can inhibit cancer cell proapoptotic factors in the body and activate anticancer cell apoptosis factors to promote cancer initiation and progression." (PMID 35586809, 2022). "The results from KEGG analysis indicated that pathways including cell cycle and mTOR signaling pathway were particularly enriched, which were closely related to cancer progression." (PMID 35607442, 2022). "In support, Beckman and colleagues and others proved that ceramidase is able to induce oncogenic Akt/mTOR and K-Ras/Erk signaling in different types of cancers." (PMID 36010601, 2022). "Accordingly, one study has evaluated mTOR and Hsp90 inhibitors in combination in TSC1 or TSC2 deficient cancer models." (PMID 35883484, 2022). "On the other hand, dysregulated mTOR signaling plays a role in cancer, Alzheimer’s disease, and type 2 diabetes." (PMID 35788771, 2022). "It has been reported that MALAT1 regulates cancer metabolism and the Warburg effect via the mTOR pathway in HCC, and also regulates MYBL2 expression level in HCC by affecting the alternative splicing of its pre-mRNA." (PMID 35557985, 2022). "If it is more coincidental that the mTOR pathway in the patient’s cancer tissue is activated, then mTOR inhibitor AZD8055 can be more accurately selected for treatment." (PMID 35844514, 2022). "In conclusion, the oncogenic pathways including PI3K/Akt/mTOR signaling pathway represent a class of candidates in targeted cancer therapies due to their important oncogenic functions in regulating cell apoptosis." (PMID 35372044, 2022). "AMPK/mTOR signaling pathway is highly related to cellular energy in cancer cells and enriched in our KEGG pathway analysis." (PMID 35813859, 2022). "mTOR pathway is also a mediator for other metabolisms in various cancers, and fatty acid, cholesterol, one-carbon, and amino acid metabolisms are gaining attention in PCa research." (PMID 35557985, 2022). "Rapamycin (sirolimus) is an allosteric inhibitor of mTOR, and is now used for cancer treatment, anti-aging efforts, and other clinical uses." (PMID 35326708, 2022). "PI3K/ATK/mTOR and Ras/MAPK pathway activation are involved with constitutive PD-L1 regulation in many cancers; loss of PTEN or mutations in PIK3CA lead to PI3K/ATK/mTOR pathway activation, while mutations in EGFR or Ras lead to Ras/MAPK pathway activation." (PMID 35164673, 2022).
cancer (continued). "Since EVP4593 was shown to inhibit mTOR signaling in cancer, we anticipated the induction of autophagy upon EVP4593 treatment." (PMID 36555369, 2022). "PI3K/AKT/mTOR pathway inhibitors combined with RT is a new method to enhance radiosensitivity and for treatment in some different cancers such as CC, and mTOR inhibitors possess a possible function to promote the efficacy of RT." (PMID 35485300, 2022). "PI3K/AKT/mTOR signaling is a therapeutic targeting pathway for the development of cancer treatment, which is activated aberrantly in many human cancers." (PMID 35056702, 2022). "In this updated review, we discuss the usage of sirolimus-derived compounds and other drugs in several preclinical or clinical studies as well as explain some of the challenges involved in targeting mTOR for treating various human cancers." (PMID 36109789, 2022). "Previous studies have indicated that the PI3K/AKT/mTOR pathway is one of the most important pathways in cancer progression, while it is also one of the most promising targets for cancer therapy." (PMID 35402614, 2022). "Mutations in genes encoding proteins such as PTEN, TSC1/2, serine threonine kinase 11 (LKB1) and NF1 that lie upstream of the mTOR complexes generate cancer syndromes." (PMID 35001007, 2022). "The PI3K/AKT/mTOR (phosphatidylinositol 3-kinase/protein kinase-B/mechanistic target of rapamycin) signaling pathway is one of the most signally altered in cancer." (PMID 35328644, 2022). "Monotherapy and the combined treatment with mTOR inhibitors are widely used in clinical and pre-clinical trials in different cancers." (PMID 35485300, 2022). "The PI3K/AKT/mTOR signaling pathway plays key role in cancer, as is related to cell proliferation, angiogenesis, chemotherapy resistance, and several other pathological conditions." (PMID 35299895, 2022). "The Akt-mTOR signal is important for the survival and proliferation of cancer cells and has become an interesting drug target." (PMID 36500361, 2022). "Anti-cancer drugs containing morpholine interacting moieties include inhibitors of the PI3K/Akt/mTOR signaling pathway, perhaps one of the most commonly altered signaling pathways in cancer." (PMID 35890360, 2022). "The effect was accompanied by decrease in the expression of mTOR-potent cancer growth stimulator and an increase in p-AMPKα expression, a sensor of ATP level." (PMID 35409177, 2022). "Due to its vital role in case of microbial infections, inflammations and cancer development and progression, mTOR has been considered as a key therapeutic target for the development of targeted medication." (PMID 36293326, 2022). "Seventy-one cancer patients with activation of the mTOR pathway were offered an mTORC1-inhibitor-based targeted therapy, and twenty-three (32.4%) of them eventually received the targeted therapy." (PMID 35454843, 2022). "Due to various genetic mutations, Akt-mTOR overactivation is often detected in NSCLC, which is associated with tumorigenesis and cancer progression." (PMID 35831279, 2022). "Note that all the cancer cell lines expressed similar mTOR levels when compared to the mTOR-expressing PCa cell lines (PC-3 and MDa PCa 2b)." (PMID 36077039, 2022). "Dysregulation of the mTOR signalling pathway is involved in many diseases, such as cancers, neurodegenerative diseases, and diabetes mellitus." (PMID 35883796, 2022). "Recent discoveries evaluating the genetic causes of VAs have revealed that they are due to mutations in cancer pathways, including the PI3K/AKT/mTOR and RAS/MAPK/MEK pathways." (PMID 35253343, 2022). "The pattern B was significantly enriched in cell cycle and cancer-associated pathways, including DNA replication, PI3K/AKT/mTOR signaling." (PMID 36091162, 2022). "Our patients were switched to mTOR inhibitor therapy, mainly due to malignant tumors acquired before or after transplantation." (PMID 35505648, 2022).